HNF1A (HNF1 homeobox A)
Diseases named in the same sentence as HNF1A in open-access papers (continued):
Sharing a sentence is not in itself a finding about the gene and the disease.
lipid metabolism disorders (2 papers, 2022). "Thus, our findings may potentially provide more insights into the study of the sex-specific biological pathways mediating lipid metabolism and involving HNF1A transcriptional machinery, which would identify potential therapeutic targets for the treatment of patients with lipid metabolism disorders." (PMID 35109885, 2022).
liver neoplasm (2 papers, 2018 to 2020). Tumors or cancers of the LIVER. "Somatic deletion of the second allele of HNF1A was found in liver tumor tissues in both probands who were diagnosed with HCA." (PMID 31754975, 2020). "Lower serum miR-122 is a unique feature of HNF1A-DM patients and might partially explain the increased risk for liver neoplasm and abnormal lipid metabolism in HNF1A-DM patients." (PMID 30155490, 2018). "The low serum miR-122 might partially explain the increased risk of liver neoplasm and abnormal lipid metabolism associated with HNF1A-DM." (PMID 30155490, 2018).
pancreatic adenocarcinoma (2 papers, 2015 to 2022). "In conclusion, we have shown that HNF1A expression is significantly decreased in human pancreatic adenocarcinoma tumors." (PMID 25793983, 2015). "HNF1A was expressed in three out of eight pancreatic adenocarcinoma cell lines and the level of HNF1A mRNA and protein expression was significantly lower in tumors than in normal adjacent tissues by both RT-PCR and Western Blot analyses." (PMID 25793983, 2015). "First, reduced expression of HNF1A was detected in human pancreatic adenocarcinoma at both mRNA and protein levels." (PMID 25793983, 2015). "In fact, CDKN2B and HNF1A deletions/inactivations have been evidenced in pancreatic adenocarcinoma." (PMID 34668636, 2022).
polycystic ovary syndrome (2 papers, 2017 to 2024). A disorder that manifests as multiple cysts on the ovaries. "Previous studies have suggested that GGT1 and HNF1A genes may contribute to the abnormal glucose metabolism and altered lipid profile observed in Polycystic ovary syndrome, a significant clinical feature of the disorder." (PMID 38233749, 2024). "Among the 14 HNF1A-MODY individuals, 12 were on SU, one patient (a 30-year female with polycystic ovary syndrome) was on metformin, and one was on dietary therapy only." (PMID 28593615, 2017).
prediabetes (2 papers, 2021 to 2022). "The lack of enrichment of prediabetes in individuals with HNF1A and HNF4A variants in unselected cohort suggest that these individuals do not have enrichment of milder subclinical disease." (PMID 36257325, 2022).
renal dysfunction (2 papers, 2015 to 2022). "For example, a study involving 11 HNF1A-MODY patients in Japan found that about 36% of HNF1A-diabetic patients experienced renal dysfunction." (PMID 35299962, 2022).
renal fibrosis (2 papers, 2023 to 2025). A final common manifestation of a wide variety of chronic kidney diseases characterized by glomerulosclerosis and tubulointerstitial fibrosis. "This demonstrates that asperulosidic acid can up-regulate OAT protein expressions via increasing HNF1α to accelerate the excretion of IS and then alleviates the progression of renal fibrosis." (PMID 38067420, 2023). "Unfortunately, to date, the relationship among HNF1α, NF-κB and TGF-β1 was unclear, and a further experiment to confirm it using multi-omics technology will be conducted in order to understand comprehensively the benefits of asperulosidic acid in renal fibrosis improvement." (PMID 38067420, 2023).
teratoma (2 papers, 2021 to 2022). A non-seminomatous germ cell tumor characterized by the presence of various tissues which correspond to the different germinal layers (endoderm, mesoderm, and ectoderm). "While 87.9% (51/58) of mice transplanted with isogenic HNF1A-MODY iPSC Het (+/R200Q) and R200Q-corrected WT (+/+) lines were teratoma-free, the majority (61.5%, 8/13) of the HNF1A-MODY iPSC Het (+/460ins) and control iPSC WT lines showed teratoma formation." (PMID 35918471, 2022).
viral infection (2 papers, 2019 to 2023). "Given that both HNF1A and HNF1B motifs were enriched in mSWI/SNF-dependent sites and both HNF1 family transcription factors mediated viral infection, yet only HNF1A was shown to bind BAF complexes, we performed reciprocal immunoprecipitations to determine whether HNF1A/B factors dimerized." (PMID 36894709, 2023). "Notably, a number of additional genes localized to SMARCA4-dependent genomic regions were those found to mediate viral infection in our CRISPR screen along with ACE2, such as SLC4A4 and HNF1A, thus suggesting that mSWI/SNF complexes regulate a coronavirus susceptibility gene expression axis." (PMID 36894709, 2023).
-dependent (1 paper, 2023). "Previous research indicated that HNF1A-KO mice exhibit a phenotype resembling Laron-type dwarfism and non–insulin-dependent DM, likely due to a decrease in the expression of insulin-like growth factor I and lower insulin levels." (PMID 37219942, 2023).
breast tumors (1 paper, 2024). "In addition to known TFs such as GATA3 and FOXP1, we identify HNF1A as a TF specific to luminal A/B breast tumors and LM breast duct cells." (PMID 39478117, 2024).
cardiomyopathy (1 paper, 2022). A disease of the heart muscle or myocardium proper. "We identify multiple drugs, genetic perturbations, and diseases that are associated with the expression of ACE2, including cardiomyopathy, HNF1A overexpression, and drug treatments with RAD140 and itraconazole." (PMID 35012625, 2022). "Using GENEVA, we identified multiple drugs, genetic perturbations, and diseases that modulate the expression of ACE2, including cardiomyopathy, HNF1A overexpression, and drug treatments with RAD140 and itraconazole." (PMID 35012625, 2022). "We identified multiple drugs, genetic perturbations, and diseases that modulate the expression of ACE2, including cardiomyopathy, HNF1A overexpression, and drug treatments with RAD140 and itraconazole." (PMID 35012625, 2022).
cholelithiasis (1 paper, 2025). The presence of crystallized deposits forming in the gallbladder or biliary tree, primarily composed of cholesterol, bilirubin, and bile. "Seven genes, including GCKR, SNX17, ABCG8, MARCH8, FUT2, APOH, and HNF1A, were revealed to be colocalized with the causal signal between sphingomyelin and cholelithiasis." (PMID 40428345, 2025).
colonic adenomas (1 paper, 2010). "The mTOR signalling pathway, whose activation has been functionally linked to the development of many cancers including colonic adenomas, was found to be up-regulated in Hnf1α null intestinal epithelium and could be responsible for the amplification of crypt proliferation and intestinal growth." (PMID 20808783, 2010).
cystinosis (1 paper, 2025). Cystinosis is a metabolic disease characterized by an accumulation of cystine inside the lysosomes, causing damage in different organs and tissues, particularly in the kidneys and eyes. "Indeed, loss of Hnf1a and Hnf4a expression has been implicated in the development of proximal tubular dysfunction, resulting in glycosuria and polyuria, which are hallmark features of cystinosis." (PMID 40917744, 2025).
deficiencies (1 paper, 2023). "As E1S is the main source of nephroprotective estradiol in humans, decreased E1S uptake may partly account for renal deficiencies in patients with HNF1A gene mutations." (PMID 37137894, 2023).
depression (1 paper, 2023). "Three of these genes (NEGR1, TMEM106B, HNF1A) have been linked to each of the three diseases (CAD, T2D and depression) in previous studies, supporting their probable involvement in psycho-cardiometabolic multimorbidity." (PMID 37390107, 2023).
dwarfism (1 paper, 2023). "However, direct deletion of Hnf1a in mice or deleterious mutations in HNF1A in humans do not appear to confer any lifespan advantage despite the mice having a form of Laron dwarfism and humans have lower BMI." (PMID 37691384, 2023).
fibrolamellar carcinoma (1 paper, 2019). "Loss of L-FABP and HNF-1α inactivation is a consistent feature of fibrolamellar carcinoma while HNF-1α mutation is an important occurrence in fibrolamellar carcinoma pathogenesis." (PMID 31685031, 2019).
glomerulonephritis (1 paper, 2025). A renal disorder characterized by damage in the glomeruli. "In Patient 18, who was diagnosed with glomerulonephritis and retinoblastoma, an LP variant in the HNF1A gene associated with DM was detected." (PMID 40718208, 2025).
gout (1 paper, 2021). A condition characterized by painful swelling of the joints, which is caused by deposition of urate crystals. "Among other results, this study highlighted genetic correlations of urate with gout and various metabolic traits; tissue enrichment signals in kidney and liver; and genetic signals at the master regulators for kidney and liver development HNF1A and HNF4A." (PMID 33587031, 2021).
hyperuricemia (1 paper, 2025). An abnormally high level of uric acid. "Hyperuricemia has a strong genetic component (40%–70%): related genes include SNPs in SLC22A12, ABCG2, HNF1A, and HNF4A." (PMID 41195208, 2025).
hypothyroidism (1 paper, 2022). Abnormally low levels of thyroid hormone. "MODY3 patients suffer from renal dysplasia, growth hormone deficiency, and hypothyroidism, which is similar to homozygous HNF1A knockout mice, which exhibit stunted growth, reduced size, and weight 50%–60% less than their wild-type counterparts." (PMID 36361703, 2022).
keloid (1 paper, 2020). An irregularly shaped, elevated mark on the skin caused by deposits of excessive amounts of collagen during wound healing. "Importantly, by binding the upstream target gene of GLI2 and neighboring target gene HNF1A separately, the lncRNA-AC073257.2 and lncRNA-HNF1A-AS1 could both affect cell keloid growth and proliferation." (PMID 33243301, 2020).
laryngeal carcinoma (1 paper, 2026). Carcinoma that arises from the laryngeal epithelium. "Contemporary evidence has confirmed that HNF1A binds to the promoter region of CRP, thereby upregulating CRP expression and promoting laryngeal cancer progression." (PMID 41583511, 2026).
lipodystrophy (1 paper, 2019). A congenital or acquired disorder characterized by abnormal loss or redistribution of the adipose tissue in the body. "In view of the pivotal role of HNF1α and HNF4α in the lipid metabolism and maintenance of serum cholesterol concentration in lipectomized rats, one may ask how these findings translate onto humans subjected to liposuction (or humans with lipodystrophy)." (PMID 30483910, 2019).
Lynch syndrome (1 paper, 2014). An autosomal dominant hereditary neoplastic syndrome characterized by the development of colorectal carcinoma and a high risk of developing endometrial carcinoma, gastric carcinoma, ovarian carcinoma, renal pelvis carcinoma, and small intestinal carcinoma. "One of the variants was previously reported to cause Lynch syndrome (MLH3) and the other to cause Renal cell carcinoma/MODY type 3 (HNF1A)." (PMID 24884844, 2014).
meningioma (1 paper, 2024). A generally slow growing tumor attached to the dura mater. "Variants typical for angiomatous (brain) meningioma are PIK3CA, KIT, PTPN11, CDH1, SMAD4, and SMARCB1; the variants typical for psammomatous meningioma are APC, FGFR2, HNF1A, STK11, and JAK3." (PMID 38476782, 2024).
metastatic colorectal cancer (1 paper, 2017). "We examined whether HNF1A polymorphisms are associated with clinical outcomes in two independent cohorts combining 417 European ancestry patients with metastatic colorectal cancer (mCRC) treated with irinotecan-based chemotherapy." (PMID 29066969, 2017).
metastatic tumors (1 paper, 2025). "FFPE liver sections showed a significant increase in total metastatic tumor area from 5.5% of the total liver area in the LacZ livers to over 20% in the HNF1A livers." (PMID 40731412, 2025). "Knockdown of HNF1A significantly depleted metastatic tumors, and HNF1A overexpression significantly increased cell migration and invasion in several PDAC cell lines, which was abrogated by FGFR4 genetic knockdown and pharmacological inhibition." (PMID 40731412, 2025). "Based on the strong correlation between HNF1A and FGFR4 expression in metastatic disease, we next sought to validate FGFR4 as a direct target gene of HNF1A." (PMID 40731412, 2025). "Using RNA-sequencing datasets from the European Genome Phenome Archive EGAD00001003584 and EGAD00001004548) and CPTAC, we additionally found a positive and significant correlation in HNF1A and FGFR4 RNA levels in patient samples from both primary and metastatic tumors." (PMID 40731412, 2025). "As HNF1A overexpression has previously been shown to increase cell proliferation, we further sought to validate that the metastatic tumors from mice inoculated with HNF1A overexpressing cells were not larger simply because they proliferated more rapidly." (PMID 40731412, 2025).
neuroendocrine tumors (1 paper, 2020).
neutropenia (1 paper, 2017). A decrease in the number of neutrophils found in the blood. "Thirteen HNF1A htSNPs were assessed for their association with OS, PFS, response rate, severe gastrointestinal toxicities and severe neutropenia." (PMID 29066969, 2017).
ovarian dysfunction (1 paper, 2024). The inability of the ovaries to function. "We therefore assumed that in our patient, the ovarian dysfunction might be related to altered HNF1A gene expression." (PMID 38311659, 2024).
pancreatitis (1 paper, 2015). Inflammation of the pancreas. "A recent study conducted in a pancreatitis animal model has shown an injury-responsive down-regulated expression of HNF1A in acinar cells, which was related to an increased acinar cell proliferation and reduced digestive enzymes." (PMID 25793983, 2015).
polycystic kidney disease (1 paper, 2013). A usually autosomal dominant and less frequently autosomal recessive genetic disorder characterized by the presence of numerous cysts in the kidneys leading to end-stage renal failure. "For example, a renal-specific inactivation of Hnf1α in mice has been implicated in polycystic kidney disease and shown to mediate the down-regulation of several cystic disease genes localised to primary cilia, including Ift88 and Ift122." (PMID 23326503, 2013).
premature ovarian failure (1 paper, 2024). "Nevertheless, the data herein provide evidence that HNF1A is expressed in the human ovary as from the fetal stage, in certain cases, deranged expression, either independently or combined with other molecular derangements or adverse environmental factors, might lead to premature ovarian failure." (PMID 38311659, 2024).
renal cell carcinoma (1 paper, 2025). "Immunofluorescence experiments showed that S100A2 and HNF1A were significantly co-localized in the nucleus in clear renal cell carcinoma cells and in HEK293T cells, supporting the interaction between S100A2 and HNF1A." (PMID 40011447, 2025).
Syndromic (1 paper, 2023). "Syndromic disorders associated with impaired glucose metabolism and early-onset diabetes may manifest with CHI in early infancy as a common pattern (HNF4A, HNF1A microdeletion, EIF2S3)." (PMID 37065762, 2023).
wasting syndrome (1 paper, 2010). "A defect in the expression of several lipids and glucose transporters as well as intestinal lumen-to-blood glucose delivery from epithelial cells could suggest an alteration in nutrient absorption that might also contribute to the wasting syndrome driven by the loss of Hnf1α." (PMID 20808783, 2010).
tumor (86 papers, 2011 to 2026). "We further investigated the influence of HNF1A SNPs on the clinicopathological characteristics of PCa, including pathologic T and N stages, Gleason grades, clinical T stage, tumor invasion, and D'Amico risk classification." (PMID 41583511, 2026). "Certain HCAs found in MODY3 families contain a somatic mutation in one allele within the tumor and a heterozygous germline mutation in the other allele, showing the tumor-suppressive role of HNF1A in the liver." (PMID 35328643, 2022). "For example, hepatocellular adenomas (HCAs), benign liver tumors, are classified into eight subgroups based on genotypes; one subgroup is defined by inactivating HNF1A mutations with a histological feature of tumor steatosis." (PMID 35328643, 2022). "Mutations in the HNFIA gene, which encodes HNF1α, a transcription factor involved in hepatocyte differentiation, result in the loss of protein expression in tumor cells." (PMID 36233225, 2022). "There have been reports of somatic mutations of the HNF1A gene amongst various human cancers signifying its role as the tumour suppressor gene." (PMID 33580750, 2021). "HNF1A has been linked to tumor suppressive role based on tumor expression but has been recently identified to promote cancer stemness and resistance to paclitaxel and tyrosine kinase inhibitors in pancreatic tumorigenesis." (PMID 32552862, 2020). "In this study, we provide a direct genetic demonstration that HNF1A, which encodes for a homeodomain transcription factor best known for its causal role in autosomal dominant diabetes, has a tumor‐suppressive function in the exocrine pancreas." (PMID 32154941, 2020). "In the current study, we found biallelic mutations in the DNA binding domain of HNF1A in the tumor tissues of the two probands." (PMID 31754975, 2020). "Of these, the most frequently mutated genes were CREBBP and CASC5 in all three tumor types, HNF1A and APC in both PDACs and PNETs, while two, four, and eight genes were mutated only in PDACs, PNETS, and INETs, respectively." (PMID 32586046, 2020). "In HCA tumor cells, we described complete HNF1A inactivation by mutation of both alleles in 35% to 45% of the cases." (PMID 23401783, 2013). "Additionally, higher HNF1A expression was associated with smaller tumor sizes and improved OS and DSS, and served as an independent prognostic factor for OS in ccRCC patients." (PMID 41338163, 2025). "The activated hepatic stellate cells (HSCs) are the cells implicated in inducing fibrosis; they do so by inhibiting HNF1α expression in hepatocytes through IL-6- and TNFα-induced expression of miR-21 and miR-146a in the hepatocytes and thus promoting tumor development." (PMID 34771521, 2021). "The somatic mutations of HNF1α in HCC attenuate the tumor suppressor function of HNF1α and may play a role in HCC development through a distinct pathway independent of HCC with β-catenin mutations." (PMID 34771521, 2021). "HNF1A was highly expressed in most tumor tissues and associated with prognosis of cancer patients." (PMID 34234870, 2021). "Furthermore, HNF1α knock-out mice exhibit tumor-associated characteristics, such as increased proliferation of hepatocytes, leading to a dramatic liver enlargement and liver function defects." (PMID 28943628, 2015). "Compared with those of HH, the ARG1, CPS1, HNF4α, and HNF1α expression levels in tumor cell lines are minimal, if at all." (PMID 40963742, 2025). "To determine if HNF1A and FGFR4 expression are widely associated in PDAC patients, we utilized multispectral immunofluorescence staining of a tumor microarray of 220 PDAC patient samples." (PMID 40731412, 2025). "Bioluminescent imaging at the 4-week endpoint revealed significantly higher metastatic tumor burden in mice implanted with HNF1A expressing UM53 cells as compared to those inoculated with LacZ cells." (PMID 40731412, 2025).